CIITA (class II major histocompatibility complex transactivator)
Diseases named in the same sentence as CIITA in open-access papers (continued):
Sharing a sentence is not in itself a finding about the gene and the disease.
infection (continued). "In addition, mRNAs belonging to the MHC Class II pathway, such as MHC Class II transactivator (CIITA), which is the key molecule for MHC Class II expression, were also induced at D21 post infection." (PMID 21249199, 2011). "Infection of epithelial cells provides potential in vivo significance to this study, especially considering that thymic epithelial cells constitutively express MHC class II (and thus CIITA)." (PMID 20585587, 2010). "However, the same study reported that CIITA overexpression did not inhibit infection by vesicular stomatitis virus pseudotyped with LASV glycoprotein." (PMID 40579376, 2025). "We therefore tested whether there was any difference in Vero cells when CIITA was driven by the H6 promoter rather than the SP promoter, with a high expression seen after infection with FPCIITAH6." (PMID 29385169, 2018). "In CIITA-transgenic mice, which have a substantial population of IL-4-induced innate CD8+ T cells, this population facilitated rapid control of viremia and induction of functional anti-viral T-cell responses during infection with chronic form of lymphocytic choriomeningitis virus." (PMID 26452143, 2015). "Likewise, the IFN-γ-induced acetylation of histone H3 at CIITA pIV, but not at β-actin was significantly reduced following infection with T. gondii (p = 0.006)." (PMID 22275866, 2012).
infectious disease (2 papers, 2014 to 2023). A disorder directly resulting from the presence and activity of a microbial, viral, or parasitic agent in humans. "Our study has demonstrated that CIITA recruitment commonly occurs outside the MHC, often not in the setting of a classical enhanceosome with RFX5, and involves genes enriched for immune function and infectious disease." (PMID 25366989, 2014).
inflammatory myopathy (1 paper, 2023). "Expression levels of the 10 most significantly expressed genes of the IFN‐signaling pathway and CIITA in different subtypes of inflammatory myopathy." (PMID 36882048, 2023).
CIITA also shares sentences with these, for which no sentence is quoted: myocardial infarction (3 papers); inflammation (2); metastatic melanoma (2); squamous cell carcinoma (2); acute monocytic leukemia (1); adenocarcinoma (1); Adrenal insufficiency (1); Arthritis (1); Autoimmune Addison's disease (1); autoimmune myocarditis (1); autoimmune polyglandular syndrome (1); bacterial infection (1); bipolar disorder (1); celiac disease (1); demyelinating disease (1); diarrhoea (1); Ebola (1); Epstein-Barr virus infection (1); Ewing sarcoma (1); gastrointestinal disease (1); granulosa cell tumour (1); hemorrhage (1); inflammatory bowel disease (1); influenza (1); keratoconus (1); latent infection (1); leishmaniasis (1); leprosy (1); Lewis Lung carcinoma (1); medulloblastoma (1).
A further 17 diseases each share a sentence with CIITA in 1 paper.